IL1B (interleukin 1 beta)
Diseases named in the same sentence as IL1B in open-access papers (continued):
Sharing a sentence is not in itself a finding about the gene and the disease.
insulinoma (24 papers, 2010 to 2025). "Using 832/13 and INS-1E rat insulinoma cells and isolated rat islets, we provide evidence that apoptosis is unlikely to be the primary pathway underlying β-cell death in response to IL-1β+γ-IFN." (PMID 21829464, 2011). "Like insulinoma cells, IL-1β stimulated NOS2 expression in rat islets was attenuated in the presence of I-BET151." (PMID 36176467, 2022). "Next, we exposed the 832/13 rat insulinoma cell line to either IL-1β or IL-1β after one pre-treatment in the presence of either PMI 5011 or DMC2." (PMID 35625635, 2022). "It was also reported that Gadd45β overexpression inhibited JNK activation and suppressed IL-1β-induced apoptosis in the insulinoma cells." (PMID 34769468, 2021). "Third, pre-treatment of 832/13 rat insulinoma cells with GNF-9228 is cytoprotective against the ER stress-inducing agent thapsigargin or a mixture of the cytotoxic cytokines IL-1β + γ-IFN." (PMID 32176701, 2020). "In rat insulinoma cell line, FN blocked IL-1β-induced NF-κB activation and consequent iNOS expression and NO production." (PMID 31561418, 2019). "To this purpose, we first exposed the mouse insulinoma cell line β-TC3 to chronic treatment with IL-1β + IFN-γ, generating a cytokine-resistant cell line (β-TC3R)." (PMID 22393382, 2012). "To this purpose, we created a cytokine-resistant β-cell line (β-TC3R) by chronically treating with IL-1β + IFN-γ the cytokine-sensitive murine insulinoma β-TC3 cell line." (PMID 22393382, 2012). "To this purpose, we created a cytokine-resistant β-cell line (β-TC3R) by chronically treating the β-TC3 murine insulinoma cell line with IL-1β + IFN-γ." (PMID 22393382, 2012). "In 832/13 rat insulinoma cells, we observed that 1 ng/mL IL-1β is sufficient to drive maximal expression of the CCL2 gene, as increasing the amount 10-fold to 10 ng/mL does not promote additional mRNA accumulation." (PMID 23056550, 2012). "The aim of the present study was to assess possible in vitro effects of formononetin on cell apoptosis induced by IL-1β in the rat insulinoma cell line, INS-1." (PMID 22922276, 2012). "In summary, we have demonstrated a profound inhibitory effect of resveratrol on IL-1β-induced dysfunction of β-cells using an insulinoma cell line and isolated rat pancreatic islets." (PMID 23554653, 2010). "In addition, formononetin attenuates hydrogen peroxide- and IL-1β-induced activation of NF-κB in retinal ganglion cells and the insulinoma cell line INS-1, respectively." (PMID 29312829, 2018). "Thus, the immunofluorescence assays reveal that in contrast to the mast cell, where Dex prevents nuclear translocation of p65, no such blockade in trafficking exists in glucocorticoid-treated 832/13 rat insulinoma cells that are also exposed to IL-1β." (PMID 23056550, 2012). "β-cell apoptosis is induced when tumor necrosis factor α or IL-1β, along with IFN-γ, is applied to human and animal islets and insulinoma cells." (PMID 39968090, 2025). "Using insulinoma INS 832/13 cells and isolated rat pancreatic islets, we examined the role of BET proteins in regulating proinflammatory gene expression following IL-1β stimulation." (PMID 36176467, 2022). "In addition, PRDX6 protected rat insulinoma RIN-m5F β cells, cultured with TNF-α and IL-1β, against the cytokine-induced cytotoxicity and reduced the apoptotic cell death and production of ROS." (PMID 32908936, 2020). "Similarly, miR-21, miR34a, and miR-146a increased significantly through the induction of IL-1β and TNF-α in mouse insulinoma 6 (MIN6) cells." (PMID 33233727, 2020). "By exposing NIT1 insulinoma cells and rat islets to a cocktail of pro-inflammatory cytokines (TNFα and IL1β), we mimicked inflammatory signaling as seen by JNK and NFκB activation and increased mRNA levels of TNFα, IL1β and NOS2a." (PMID 24974801, 2014).
insulinoma (continued). "Moreover, the GPR40 agonists could reduce inflammatory signaling, such as NF-κB, IL-1β, TNF-α, and NOS2α, in the mouse NIT1 insulinoma cells and rat islets that are under chronic inflammatory conditions and LPS-induced activation of IKK in BV2 cells." (PMID 30981281, 2019).
intracerebral hemorrhage (24 papers, 2014 to 2025). A cerebrovascular disorder characterized by bleeding into one or both cerebral hemispheres including the basal ganglia and the cerebral cortex. "(2024) reported that exosomes derived from MSCs preconditioned with interleukin-1β (IL-1β-Exos) significantly inhibited neuronal ferroptosis in a rat model of intracerebral hemorrhage (ICH)." (PMID 41190075, 2025). "In murine intracerebral hemorrhage models, Cerebrolysin-treated animals exhibited significant reductions in IL-1β, IL-6, and TNF-α, as well as in aquaporin-4 (AQP4)—a main mediator of vasogenic edema." (PMID 40362194, 2025). "Microglial Tim3 expression is increased following intracerebral hemorrhage, and Tim3 knockdown mitigates intracerebral hemorrhage-induced brain damage accompanied with diminished IL1β secretion." (PMID 41177809, 2025). "MCC950 preserves the blood–brain barrier (BBB) and decreases cell death by downregulating NLRP3, caspase-1, and IL-1β production in mice with intracerebral hemorrhage." (PMID 35219323, 2022). "A recent study reported that intracerebral hemorrhage disrupts the blood–brain barrier (BBB) function via activation of IL-1β/RhoA/ROCK/NFκB signaling, which results from increased degradation of the inhibitor of κB (IκB)." (PMID 35215244, 2022). "Previous studies have shown that QUIN decreases IL-1β and MCP-1 levels by suppressing the CRYAB/NF-kB inflammatory pathway in an intracerebral hemorrhage model, and this change was associated with reduced microglial activation." (PMID 36278007, 2022). "Through the inhibition of the TLR4/NF-κB pathway, the secretion of TNF-α, IL-6, and IL-1β decreases, and the injury to the brain due to intracerebral hemorrhage can be attenuated." (PMID 33133217, 2020). "Inhibition of microglia inflammation by reduction of NF-κB activation and by the attenuation of TNF-α, IL-1β,IL-6, and reactive oxygen species (ROS) protects the brain from intracerebral hemorrhage and MDD." (PMID 30356873, 2018). "Similarly, a VDAC dimer has been reported to increase ROS production, as well as nucleotide oligomerization domain (NOD)-like receptor family pyrin domain containing 3 (NLRP3) and IL-1β levels in the mouse brain with intracerebral hemorrhage." (PMID 33803845, 2021). "It has been demonstrated that NLRP3 activation and formation of NLRP3 inflammasome in microglia surrounding hematoma after intracerebral hemorrhage promotes caspase-1 activation and leads to increased expression of IL-1β/IL-18, inducing and exacerbating aseptic inflammatory response." (PMID 34526897, 2021). "For instance, in the model of intracerebral hemorrhage, Dectin-1 signaling pathway upregulates the expression of GSDMD-N, IL-1β and IL-18 in mouse brain cells." (PMID 38459541, 2024). "To date, researchers have demonstrated that large amounts of inflammatory cytokines, such as IL-1β, IL-6, TNF-α, can be detected around hematomas after intracerebral hemorrhage in humans and animals." (PMID 34526897, 2021). "Metformin downregulated the expression levels of inflammatory cytokines (IL-1β, IL-4, and IL-6 and TNF-α) in intracerebral hemorrhage model rats." (PMID 32831980, 2020). "In the development of intracerebral hemorrhages, the expression of Toll-like receptor 4 (TLR4) is enhanced, and this could lead to an increase in the levels of TNF-α, IL-6, and IL-1β through the TLR4/NF-κB pathway, followed by aggravation of brain lesions." (PMID 33133217, 2020).
pulpitis (24 papers, 2015 to 2026). Inflammation of the dental pulp. "Following the onset of pulpitis, the increased secretion of the IL-1β from exosomes is crucial for sustaining persistent pain, and this mechanism is regulated by microglial P2X7R in the MDH." (PMID 39987146, 2025). "Overall, our study revealed that Rab27a was upregulated in the MDH of rats with pulpitis and that the exosomes were enriched in IL-1β, indicating increased exosome secretion during the occurrence of pain." (PMID 39987146, 2025). "Compared with the control, pulpitis induction resulted in increases in the secretion of exosomes and the inflammatory factor IL-1β in the MDH, which exhibited similar trends." (PMID 39987146, 2025). "In summary, our findings confirm that exosomes play an important role in pulpitis-induced pain modulation and that microglial P2X7R regulates pulpitis-induced pain by controlling the secretion of inflammatory exosomes containing IL-1β." (PMID 39987146, 2025). "Its expression increases progressively during irreversible pulpitis and correlates significantly with pro-inflammatory cytokines (interleukin-1beta (IL-1β), IL-6, tumor necrosis factor-alpha (TNF-α))." (PMID 40708698, 2025). "Both IL-1β and TNFα are typical proinflammatory cytokines participating in the pathological process of pulpitis." (PMID 40414936, 2025). "Our previous research demonstrated that microglial P2X7R in the MDH promoted the release of IL-1β and contributed to the occurrence of pulpitis-induced pain." (PMID 39987146, 2025). "Our research highlights a new pulpitis mechanism in which exosomes enriched with IL-1β contribute to pulpitis-induced pain, suggesting the crucial roles of exosomes as pain biomarkers and harmful signaling molecules during pulpitis." (PMID 39987146, 2025). "Lipopolysaccharide (LPS) is a potent stimulator of pulpitis that has been found in inflamed pulp tissue, causing the release of inflammatory cytokines including TNF-α, IL-1β, and IL-6." (PMID 36788505, 2023). "In this regard, the results of a reversible pulpitis model showed that IL-1β, IL- 6, and TNF-α gene expressions were elevated in LPS-exposed inflamed pulp tissues." (PMID 36788505, 2023). "The overexpression of miR‐126 delivered by PEI effectively downregulated VCAM‐1 and the IL‐1β, a key pro‐inflammatory cytokine in pulpitis, under LPS challenge in vitro." (PMID 35334501, 2022). "IL-1β is one of the essential mediators of acute dental pulp inflammation, and the increase of IL-1β level in dental pulp tissue aggravates the pulp inflammation." (PMID 35413908, 2022). "For example, let-7c attenuated the severity of pulpitis by inhibiting the NF-κB pathway in inflammatory disorders as NF-κB pathway increased the production of the inflammatory cytokines IL-1β and TNF-α and decreased stem cell viability." (PMID 32960786, 2020). "Dental pulps with pulpitis suffer higher expressions of proinflammatory cytokines (IL-1α, IL-1β, IL-6, and TNF-α) and innate immune response (TLR2, TLR4) than pulps without pulpitis." (PMID 31695620, 2019). "The expression of NLRP3, caspase-1 and IL-1β was analysed by the detection of the relevant protein and mRNA in normal pulp and in pulp with reversible pulpitis or irreversible pulpitis." (PMID 25684031, 2015). "A significant difference in the mRNA level of caspase-1 and IL-1β was observed only between normal pulp and pulp with irreversible pulpitis." (PMID 25684031, 2015). "GW4869 and BBG inhibited Rab27a and IL-1β expression, reducing pulpitis-induced pain." (PMID 39987146, 2025). "Furthermore, Remodelin significantly lowered TNF-α and IL-1β protein levels in the dental pulp of rats with pulpitis, concurrently reducing inflammatory cell infiltration within the dental pulp tissue." (PMID 40362562, 2025). "Vascular cell adhesion molecule (VCAM‐1) mediates pulpitis via regulating interleukin (IL)‐1β." (PMID 35334501, 2022).
pulpitis (continued). "In addition, we confirmed the function of miR‐126 overexpression in reducing VCAM‐1 and interleukin 1 beta (IL‐1β), a pro‐inflammatory cytokine participating in pulpitis, in human DPCs under the stimulation of LPS." (PMID 35334501, 2022). "Also, in the stimulation of fibroblasts obtained from either healthy teeth or by pulpectomy, due to irreversible pulpitis, higher IL-1β release was found in the case of irreversible pulpitis." (PMID 33801317, 2021). "For IL-1β other authors also report measurable levels in pulp tissues even in the healthy pulp, but found significantly higher concentrations in irreversible pulpitis." (PMID 33801317, 2021). "Therefore, we aimed to investigate whether P2X7R regulates microglial Rab27a expression and IL-1β secretion in the experimental pulpitis model." (PMID 39987146, 2025). "Being the critical initiator in pulpitis pathogenesis, bacterial LPS penetrates into the affected dental pulp tissue, motivates substantial release of inflammatory mediators from dental pulp, such as IL-1β, TNF-α, IL-6, and IL-8, thus triggering the inflammatory response of the dental pulp." (PMID 35413908, 2022). "IL-1β, TNF-α, and IL-6 are inflammatory mediators that have been widely reported to involve the inflammatory process and potentiate pain in pulpitis." (PMID 38627713, 2024). "Our results demonstrated IL-6, TNF-α TNF, IL-1β, CXCL8 and CCL2 are closely related to the immune infiltrating cells in pulpitis." (PMID 37179325, 2023). "It has been reported that HIF-1α promotes the expression of IL-1β and TNF-α in inflammatory dental pulp cells, and HIF-1α is involved in the development of dental pulpitis from reversible to irreversible pulpitis." (PMID 36385758, 2022). "Meanwhile, in pulpitis tissue, the protein level of NLRP3, cleaved caspase-1 and cleaved IL-1β, which also play a key role in inflammation and pyroptosis, was significantly increased." (PMID 34887391, 2021). "The western blot, qRT‒PCR, and double immunofluorescence staining results indicated that BBG decreased Rab27a and IL-1β expression, suggesting that microglial P2X7R-mediated exosome secretion may be a novel mechanism of pulpitis pain." (PMID 39987146, 2025). "In this study, employing molecular biology techniques and cell biology analyses, we propose that exosomes could serve as pivotal pulpitis-induced pain markers in the MDH and that IL-1β is released from these enhanced exosomes via microglial P2X7R regulation." (PMID 39987146, 2025). "Gene expression profiles and bioinformatics analysis confirmed that M0 macrophages and neutrophils play an irreplaceable role in pulpitis immunity, and the critical genes in the immune reaction to pulpitis are suggested to be IL-6, TNF-α, IL-1β, CXCL8, and CCL2." (PMID 37179325, 2023). "LPS effectively downregulated miR‐126 that might contribute to the pulpitis's inflammatory progression by activating VCAM‐1 and IL‐1β." (PMID 35334501, 2022). "miR‐126 is involved in pulpitis and downregulated the VCAM‐1 and IL‐1β in DPCs." (PMID 35334501, 2022). "Therefore, IL-6, TNF-α, IL-1β, CXCL8, and CCL2 may participate in the occurrence and development of pulpitis by regulating the corresponding immune cells, which needs further experimental verification." (PMID 37179325, 2023).
bacterial vaginosis (23 papers, 2007 to 2024). Infection caused by bacterial overgrowth in the vagina. "Pathogenic bacteria trigger an inflammatory response that leads to high levels of the proinflammatory cytokines IL-1β, IL-6 and IL-8, thereby causing the complications associated with bacterial vaginosis." (PMID 39479185, 2024). "The diversity of microbial communities dominated by bacteria associated with bacterial vaginosis leads to an increase in the levels of cytokines, such as IL-8, IL-1a, IL1b, interferon and tumor necrosis factor." (PMID 35359942, 2022). "Genetic polymorphisms have been reported in women with recurrent bacterial vaginosis in a variety of genes including those encoding mannose-binding lectin and IL-1β, both of which play key immune roles." (PMID 34736529, 2021). "The observed association between FGF IL-1β and bacterial vaginosis has been described in the literature." (PMID 29625077, 2018). "Notably, IL-1β has been associated with bacterial vaginosis in several studies and further explorations are needed to establish the directional link between IL-1β secretion, bacterial vaginosis and HIV genital shedding." (PMID 26010956, 2015). "For example, IL-1α, IL-1β, and tumor necrosis factor-α, along with bacterial vaginosis, may be associated with genetic polymorphisms in the innate immune Toll-like-receptor (TLR1, TLR 2, TLR 4 and TLR 9) and proinflammatory cytokines (IL-1β, IL-1ra, IL-6, IL-6, CXCL8, and IL-10)." (PMID 35359942, 2022). "Numerous investigations have indicated elevated concentrations of pro-inflammatory cytokines, including IL-1β, IL-6, and IL-8, in vaginal tissues from women with bacterial vaginosis (BV) relative to “healthy” controls." (PMID 39598357, 2024). "HEC-1A cells were incubated separately with TNF-α, IL-1β, IL-6 or IL-8 at concentrations corresponding to the maximum levels of these cytokines determined in the cervicovaginal fluid of bacterial vaginosis patients." (PMID 36145684, 2022). "Prior data demonstrate that IL-1β plays a key role in mediating the inflammatory response to bacterial vaginosis." (PMID 33035192, 2021). "A consistent finding is that levels of IL-1b are increased in women with bacterial vaginosis compared to women with a genital microbiota that is dominated by Lactobacillus." (PMID 23285244, 2012). "IL-1b is increased in women with bacterial vaginosis compared to women with a genital microbiota dominated by Lactobacillus." (PMID 23285244, 2012). "We measured the relationship between bacterial vaginosis (BV) and concentrations of Interleukin-8 (IL-8), Interleukin-1β (IL-1β), and Interleukin-6 (IL-6) in cervicovaginal lavage (CVL) specimens collected longitudinally from 16 HIV-infected and 8 HIV-uninfected high-risk women." (PMID 18273408, 2007). "In AV, there is a significant increase in IL-1β levels, reaching 178.8 pg/mL, compared to bacterial vaginosis (BV) with 71.2 pg/mL and normal controls with 5.0 pg/mL (p < 0.001)." (PMID 38674294, 2024). "Previous work has correlated enhanced levels of IL-1β,IL-6, MIP-1α, and MIP-2 with a higher risk of PPROM and pretermbirth.52−54 These studies demonstrate the correlation betweenbacterial infections such as bacterial vaginosis and UPEC with anupregulation of these proinflammatory markers." (PMID 37780357, 2023). "Finally, we did not obtain test results for lower genital tract microbiology, even though it may affect the CVF VDBP level according to a reported positive correlation between bacterial vaginosis and IL-1α and IL-1β levels." (PMID 29879190, 2018). "Bacterial vaginosis was characterized by reduced IL-18 and GATA3 mRNA expression; anaerobic vaginitis was accompanied by increased IL-1b, IL-10, and TLR4 mRNA levels; increased IL-1b and TLR4 mRNAs were detected in vulvovaginal candidiasis." (PMID 38203620, 2023).
bacterial vaginosis (continued). "Similarly, numerous studies have demonstrated the occurrence of high levels of cytokines and chemokines, such as IL-1β, TNF-α, IL-6 and IL-8, in vaginal fluids of women with bacterial vaginosis (BV)." (PMID 37375053, 2023). "L. Johnsonii could inhibit bacterial vaginosis by inhibiting the expressions of COX-2, iNOS, IL-1β, and TNF-α by regulating NF-κB activation and by killing G. vaginalis." (PMID 36846767, 2023). "In cross-sectional studies, women with bacterial vaginosis (BV) and/or more diverse, non-Lactobacillus dominant communities consistently had higher concentrations of IL-1β and IL-1α than women without BV, with consistently decreased IP-10 concentrations." (PMID 36303630, 2022).